HCP5 (HLA complex P5)
Diseases named in the same sentence as HCP5 in open-access papers (continued):
Sharing a sentence is not in itself a finding about the gene and the disease.
AIDS (8 papers, 2012 to 2020). A syndrome resulting from the acquired deficiency of cellular immunity caused by the human immunodeficiency virus (HIV). "HCP5 (HLA complex P5) is an lncRNA associated with immune response, and it is associated with for example AIDS and virus-related cancers." (PMID 30567492, 2018). "Located in the HLA complex P5 (HCP5), rs2395029 is a proxy for the HLA-B*57:01 allele, the strongest protective allele against AIDS progression." (PMID 28449694, 2017). "The HCP5 rs2395029 SNP trended to association with time to AIDS 1993 or to AIDS-related death, but as previously reported, this effect was only marginal when the analysis was corrected for the effect of viral load at set point." (PMID 23750159, 2013). "Furthermore, this GWAS showed that in the ACS the HCP5 rs2395029 was also significantly associated with delayed progression to AIDS and AIDS-related death, although the effect was notably reduced when viral load at set point was included as a covariate in multivariate analysis." (PMID 22920050, 2012). "In the case of HCP5, a clearly higher frequency of the genotype TG was found in LTNP compared with HD and TP groups, and less significant with AIDS patients." (PMID 31393887, 2019). "The association of the HCP5 polymorphism at rs2395029-G with HLA-B*57:01 and HIV nonprogression to AIDS was confirmed in follow-up studies." (PMID 31137555, 2019). "Thus, based on these limited analyses, the role of HCP5 in HIV infection and AIDS remains unclear." (PMID 31137555, 2019).
psoriasis (8 papers, 2014 to 2020). An autoimmune condition characterized by red, well-delineated plaques with silvery scales that are usually on the extensor surfaces and scalp. "We found that rs3132089, a promoter variant of the HCP5 gene, is highly linked with psoriasis risk SNP rs3134792 (r2 = 0.9253) and located on the binding motif of ARNT and BHLHE40 proteins, which is predicted to result in decreased binding." (PMID 31969149, 2020). "A variant rs2395029, located on HCP5 gene body, were previously reported to be associated with psoriasis." (PMID 31969149, 2020). "The same HCP5 and HLA-B genotypes were associated with psoriasis (PS) and psoriatic arthritis (PSA) and found to be a major determinant of flucloxacillin-induced liver injury." (PMID 31137555, 2019). "Other genes, such as IL23R, PSORS1C1, HCP5, were found to be associated with psoriasis and rheumatoid arthritis." (PMID 25369137, 2014). "Another SNP in the HCP5 gene (rs2395029) was previously associated with psoriasis and psoriatic arthritis." (PMID 25369137, 2014). "Other HCP5 variants have been associated with susceptibility and autoantibody production in various autoimmune disorders, including systemic lupus erythematous, Sjögren syndrome, psoriasis, and psoriatic arthritis." (PMID 32501499, 2020). "Four of these have been previously associated with psoriasis: C6orf10, HCP5, MICA, and POUSF1." (PMID 32245788, 2020). "A different polymorphism (rs2395029) of HCP5 was associated to psoriasis and psoriatic arthritis." (PMID 30882006, 2019). "Many of the HCP5-associated diseases such as SLE, AS, psoriasis and psoriatic arthritis, myositis, obesity, and cancer are associated also with accelerated aging, morbidity, and mortality." (PMID 31137555, 2019). "Meanwhile, there is a pseudogene XXbac-BPG299F13.15 which is located in the same LD region as HLA-C and is interacting with 4 other literature reported psoriasis-associated genes (PSORS1C1, MICA, HCP5, HLA-C)." (PMID 30315195, 2018). "The authors also noted that the same significant HCP5 SNV in psoriasis and HIV infections is not surprising since psoriasis can be triggered by infection with HIV and other viruses." (PMID 31137555, 2019). "GWAS indicated that the HCP5 SNV rs2395029 was a potential marker for abacavir-induced hypersensitivity, a marker for HLA-B*57:01 in populations of mainly Caucasian or Hispanic descent, as well as flucloxacillin drug liver injury, HIV control, and psoriasis and psoriatic arthritis." (PMID 31137555, 2019).
colorectal cancer (7 papers, 2021 to 2023). A primary or metastatic malignant neoplasm that affects the colon or rectum. "HCP5 has been studied in several kinds of tumors, including ovarian, esophageal, gastric, and colorectal cancer." (PMID 37064863, 2023). "In colorectal cancer, HCP5 contributes to epithelial–mesenchymal transition in colorectal cancer through HCP5/miR-139-5p/ZEB1 axis." (PMID 34923990, 2021). "HCP5 enhances epithelial-mesenchymal transition by activating ZEB1 and targeting miR-139-5p in colorectal cancer." (PMID 35602292, 2022).
psoriatic arthritis (7 papers, 2014 to 2022). Joint inflammation associated with psoriasis. "HCP5 is a non-coding gene located in the MHC class I region, and is linked to viral interactions, neoplastic progression, and psoriatic arthritis." (PMID 29740313, 2018).
Autoimmunity (6 papers, 2014 to 2021). The occurrence of an immune reaction against the organism's own cells or tissues. "Human histocompatibility leukocyte antigen (HLA) complex P5 (HCP5) has been recognized as a key factor in cells of the immune system with potential regulatory effects in autoimmunity." (PMID 34148029, 2021). "HCP5 was mainly expressed in immune system cells and had an effect on autoimmunity." (PMID 34194477, 2021). "Interestingly, there is accumulating evidence suggesting that lncRNA, such as HCP5, has a crucial role in the development of autoimmunity by altering the adaptive and innate immune response through transcriptional and epigenetic regulation." (PMID 32501499, 2020). "HCP5 gene (major histocompatibility complex P5), located in HLA region, is expressed primarily in cells of the immune system such as spleen, blood and thymus consistent with a potential role in autoimmunity." (PMID 25369137, 2014). "Human histocompatibility leukocyte antigen (HLA) complex P5 (HCP5) was identified in 1993 and mainly expressed in immune cells with putative role in autoimmunity." (PMID 34187569, 2021).
cutaneous melanoma (6 papers, 2017 to 2022). A primary melanoma arising from atypical melanocytes in the skin. "Only one study reported that HCP5 function as the tumor suppressor in skin cutaneous melanoma, down-regulation of HCP5 was associated with a poor OS (HR = 2.97, 95% CI 1.64–5.36), advanced tumor stage, positive distal metastasis and lymph node metastasis." (PMID 34923990, 2021). "In addition, only one study reported that down-regulation of HCP5 was associated with worse OS, advanced tumor stage, positive distal metastasis and lymph node metastasis in skin cutaneous melanoma, the number of study restricted the prognostic meta-analysis." (PMID 34923990, 2021). "Three genes, i.e., CLEC7A, CLEC10A, and HAPLN3 have been reported to exhibit prognostic significance with respect to melanoma for the first time, while HCP5 has been reported to inhibit the development of cutaneous melanoma." (PMID 33868993, 2021). "Meanwhile, we evaluated the expression level and survival analysis of HCP5 in skin cutaneous melanoma (SKCM)." (PMID 34923990, 2021). "HCP5 inhibits the development of skin cutaneous melanoma through modulating miR-12/RARRES3." (PMID 35602292, 2022). "In our study as well, HCP5 was identified as a survival-relevant eRNA in cutaneous melanoma." (PMID 36338651, 2022). "For example, one study found that HCP5 level was decreased in skin cutaneous melanoma, suggesting HCP5 could function as a tumor suppressor and suppresses melanoma development by regulating RARRES3 gene expression via sponging miR-1286." (PMID 34923990, 2021). "A linear combination of six lncRNAs (LINC01260, HCP5, PIGBOS1, RP11-247L20.4, CTA-292E10.6 and CTB-113P19.5) was constructed as an indicator for the clinical outcome of patients with cutaneous melanoma." (PMID 29100423, 2017).
esophageal cancer (6 papers, 2021 to 2023). A primary or metastatic malignant neoplasm involving the esophagus. "Our study first proposed that lncRNA HCP5 is associated with the radiosensitivity of esophageal carcinoma and affected the esophageal cancer radiotherapy curative effect." (PMID 34969363, 2022). "The expression results showed HCP5 is upregulated in esophageal cancers compared to the normal tissues." (PMID 34969363, 2022). "Meanwhile, knockdown HCP5 further suppressed the proliferation and promoted the apoptosis of esophageal cancer cells treated with a 2 Gy dose of radiotherapy." (PMID 34969363, 2022). "All the expression profile results indicated that HCP5 is upregulated in esophageal cancer and is also lifted by radiation." (PMID 34969363, 2022). "LncRNA HCP5 is highly expressed in esophageal cancer and influenced the malignant behaviors of esophageal cancer cells." (PMID 34969363, 2022). "Based on our results, we first revealed that lncRNA HCP5 definitely participates in the response to radiotherapy for esophageal cancer." (PMID 34969363, 2022). "Due to HCP5 is upregulated in esophageal cancer, we constructed a lentiviral shRNA to knockdown HCP5." (PMID 34969363, 2022). "A series of radiosensitization effects data (such as D0, Dq, N, and SF2) give a shred of strong evidence that knockdown of HCP5 enhances the radiosensitivity of esophageal cancer." (PMID 34969363, 2022). "Through a series of functional experiments, we revealed that knockdown lncRNA HCP5 enhances the radiosensitivity of esophageal carcinoma by modulating AKT signaling activation." (PMID 34969363, 2022). "In summary, our results indicate that HCP5 is involved in esophageal carcinoma radiotherapy and knockdown HCP5 enhances the radiosensitivity of esophageal carcinoma by modulating AKT signaling activation." (PMID 34969363, 2022). "In all, our results concluded that HCP5 is involved in esophageal carcinoma radiotherapy and knockdown HCP5 enhances the radiosensitivity of esophageal carcinoma by modulating AKT signaling activation." (PMID 34969363, 2022). "To summary, our results indicate that HCP5 is involved in esophageal carcinoma radiotherapy and knockdown HCP5 enhances the radiosensitivity of esophageal carcinoma by modulating AKT signaling activation." (PMID 34969363, 2022). "shHCP5 + 2 Gy) to investigate whether knockdown of HCP5 could further inhibit the malignant behaviors of esophageal cancer cells combined with a single dose of radiation." (PMID 34969363, 2022). "In sum, lncRNA HCP5 is a key regulator of radiotherapy response in esophageal cancer." (PMID 34969363, 2022). "Here in this study, we attempt to elucidate whether the radiosensitivity of esophageal cancer is governed by HCP5." (PMID 34969363, 2022). "It is possible that HCP5 may regulate the radiotherapy response to esophageal cancer in another way." (PMID 34969363, 2022). "However, our study has given a complete line of evidence supporting the knockdown of HCP5 enhance esophageal cancer radiosensitivity." (PMID 34969363, 2022). "Furthermore, knockdown of HCP5 decreased the p-AKT level by miR-216a-3p/PDK1 axis to increase the radiosensitivity of esophageal cancer cells." (PMID 34969363, 2022). "As to how HCP5 functions in esophageal carcinoma radiotherapy, we speculate that lncRNA HCP5 should sever a ceRNA participating in regulation." (PMID 34969363, 2022). "However, this study dedicates to clarify if lncRNA HCP5 affects the radiosensitivity of esophageal carcinoma." (PMID 34969363, 2022). "Thus, we can conclude that knockdown HCP5 enhances the efficacy of radiotherapy for esophageal carcinoma." (PMID 34969363, 2022). "To sum up, we proposed that lncRNA HCP5 could participate in the radiotherapy of esophageal carcinoma." (PMID 34969363, 2022). "This study sets out to explore whether knockdown HCP5 enhances the efficacy of radiotherapy for esophageal carcinoma." (PMID 34969363, 2022).
esophageal cancer (continued). "A similar mechanism also exists in esophageal cancer, where YTHDF1 can directly interact with HCP5 (HLA Complex P5), enhancing the interaction between YTHDF1 and HK2 mRNA to promote aerobic glycolysis." (PMID 38202722, 2023). "Knockdown of HCP5 modulates the miR-216a-3p/PDK1 axis to inhibit AKT activation, eventually improving the radiosensitivity of esophageal cancer." (PMID 34969363, 2022). "The results indicated that HCP5 was up-regulated in most cancers, including cholangio carcinoma (CHOL), esophageal carcinoma (ESCA), acute myeloid leukemia (LAML) and pancreatic adenocarcinoma (PAAD) (|log2FC| Cutoff: 1, P-value Cutoff: 0.01)." (PMID 34923990, 2021). "The expression levels of HCP5 in esophageal cancer and adjacent noncancerous tissue were first analyzed on the TCGA database and then detected by qRT-PCR." (PMID 34969363, 2022).
pancreatic cancer (6 papers, 2019 to 2023). "By combination of results from expression, survival and correlation analysis demonstrated that MMP9/ITGB1-miR-29b-3p-HCP5 competing endogenous RNA (ceRNA) sub-network was linked to prognosis of pancreatic cancer." (PMID 31061236, 2019). "Taken all the three levels into consideration, we constructed a novel mRNA-miRNA-lncRNA triple sub-network, MMP9/ITGB1-miR-29b-3p-HCP5, which is significantly associated with prognosis of pancreatic cancer." (PMID 31061236, 2019). "As shown by existing evidence, HCP5 negatively regulates miR-214-5p to influence bioprocesses such as autophagy and apoptosis in pancreatic cancer via the miR-214-5p/HDGF axis." (PMID 37208635, 2023). "By combining expression analysis and survival analysis for these lncRNAs in pancreatic cancer using TCGA data, only 4 lncRNAs (SCAMP1, HCP5, MAL2, LINC00511) were defined as the key lncRNAs." (PMID 31061236, 2019). "Only 10 (SCAMP1, EMG1, HCP5, TUG1, MAL2, H19, LINC00511, RP11-311C24.1, RP11-400F19.6 and CTC-459F4.3) out of 90 lncRNAs were significantly upregulated in pancreatic cancer samples when compared with normal controls." (PMID 31061236, 2019).
prostate carcinoma (5 papers, 2021 to 2024). A carcinoma that arises from epithelial cells of the prostate gland. "HCP5 enhances cell proliferation of prostate cancer by targeting the miR-4656/CEMIP axis." (PMID 35602292, 2022).
thyroid cancer (5 papers, 2020 to 2022). "It has been shown that lncRNA HCP5 plays a cancer‐promoting role in several cancer types, such as pancreatic, colorectal, lung and thyroid cancers." (PMID 35810383, 2022). "Recently, it has been reported that lncRNAs, such as HLA Complex P5 (HCP5), Papillary Thyroid Carcinoma Susceptibility Candidate 1 (PTCSC1), and LINC01014, and the PI3K/Akt/mTOR pathway are in tight conjunction during ESCC pathogenesis." (PMID 35448163, 2022).
melanoma (4 papers, 2020 to 2022). A malignant, usually aggressive tumor composed of atypical, neoplastic melanocytes. "Consistent with previous studies, we observed an association between upregulated HCP5 expression and improved survival in melanoma and that HCP5 might boost the anti-tumoral immunity." (PMID 33868993, 2021). "Studies have found that patients with melanoma can be divided into high-risk groups and low-risk groups with different survival times by a molecular signature of six lncRNAs, including LINC01260, HCP5, PIGBOS1, RP11-247L20.4, CTA-292E10.6, and CTB-113P19.5." (PMID 35016686, 2022). "The four genes (CLEC7A, CLEC10A, HAPLN3, and HCP5) were also identified as meaningful anti-tumoral genes in melanoma." (PMID 33868993, 2021). "As a recognized tumor suppressor gene, lnc-HCP5 can be used as ceRNA to sponge adsorb miR-12 and further promote the expression of RARRES3 gene, thereby inhibiting the growth of melanoma cells." (PMID 33194692, 2020).
nasopharyngeal carcinoma (4 papers, 2021 to 2025). A carcinoma arising from the nasopharyngeal epithelium. "Long noncoding RNA HCP5 contributes to nasopharyngeal carcinoma progression by targeting microRNA-128-3p." (PMID 40646778, 2025).
neuroblastoma (4 papers, 2021 to 2023). Neuroblastoma (NB) is the most common solid, extracranial childhood tumor. "Recent research has found that HCP5 was upregulated in neuroblastoma tissues and promoted neuroblastoma cells proliferation." (PMID 35399723, 2022). "Previous studies have found that HCP5 was shown to regulate neuroblastoma cells activation and promoted neuroblastoma progression by acting as ceRNA to bind with miR-186-5p and regulate MAP3K2 expression." (PMID 34907261, 2021).
Premature ovarian insufficiency (4 papers, 2022 to 2026). Amenorrhea due to loss of ovarian function before the age of 40. "HCP5, a key long non-coding RNA (lncRNA), is implicated in premature ovarian insufficiency and regulates critical pathways involved in ovarian function and fertility." (PMID 41325449, 2025). "For example, it has been reported that HCP5 regulates premature ovarian insufficiency through transcriptionally modulating MSH5 to mediate DNA damage repair by YB1." (PMID 35602292, 2022). "LncRNA HCP5 helps YBX1 nuclear localization and promotes MSH5 transcription and DNA damage repair in granulosa cells from patients with premature ovarian insufficiency." (PMID 41507135, 2026).
anaplastic thyroid cancer (3 papers, 2020 to 2021). "For example, HCP5 expression level was increased in anaplastic thyroid cancer cell lines, HCP5 knockdown inhibited the cell viability and induced apoptosis via sponging miR-128-3p." (PMID 34923990, 2021). "In addition, HCP5 knockdown reduced cell viability, while elevated apoptotic rate via sponging miR-128-3p in anaplastic thyroid cancer." (PMID 34923990, 2021).
colon cancer (3 papers, 2021 to 2024). "Chen and Yun also reported the oncogenic function of HCP5 in granulosa-like tumor cells and colon tumor cells, respectively." (PMID 38071681, 2024). "TCF-4, as a component of the Wnt pathway, also works as a tumor suppressor in colon cancer and is involved in papillary thyroid carcinoma via regulation of HCP5." (PMID 35885958, 2022).
diffuse large B-cell lymphoma (3 papers, 2020 to 2023). "In diffuse large B-cell lymphoma, geniposide is able to knockdown lncRNA HCP5 thereby increasing miR-27b-3p (a target of HCP5) levels and so inhibiting cell proliferation and inducing apoptosis in this condition." (PMID 37168992, 2023). "Geniposide also significantly inhibited diffuse large B-cell lymphoma (DLBCL) cell proliferation and promoted apoptosis; this effect was at least partially mediated through the HCP5/miR-27b-3p/MET axis." (PMID 35630796, 2022).
esophageal squamous cell carcinoma (3 papers, 2023 to 2024). Esophageal squamous cell carcinoma (ESCC) is a type of esophageal carcinoma (EC) that can affect any part of the esophagus, but is usually located in the upper or middle third. "In detail, YTHDF1-regulated LncRNA HCP5 has been evidenced to involve in progression of esophageal squamous cell carcinoma." (PMID 37365581, 2023). "Based on the analysis of lncRNA expression data from gene expression omnibus (GEO) databases, it was discovered that Human Recombinant Protein 5 (HCP5) is significantly upregulated in esophageal squamous cell carcinoma (ESCC) and indicates unfavorable survival of ESCC patients." (PMID 37055798, 2023). "Recently research revealed that YTHDF1 involved in stability and degradation of multiple LncRNAs, such as LncRNA HCP5 and LncRNA DLGAP1-AS2, thus participating in regulating the progression of esophageal squamous cell carcinoma and non-small cell lung cancer, respectively." (PMID 37365581, 2023).